KAT8 (lysine acetyltransferase 8)
Diseases named in the same sentence as KAT8 in open-access papers (continued):
Sharing a sentence is not in itself a finding about the gene and the disease.
tumor (37 papers, 2013 to 2026). "Numerous studies have revealed that KAT8 and H4K16ac are intricately associated with tumor initiation, development, and progression." (PMID 40508066, 2025). "In our study, we validated the expression of KAT8 at the single‐cell level across various cancer types and explored its association with the functional status of tumours." (PMID 40259204, 2025). "In summary, KAT8 enhances the translation of tumour‐associated proteins by mediating eEF1A2‐K408la, ultimately leading to tumour progression." (PMID 40984037, 2025). "Reduced expression levels of MYST HATs except KAT8 were significantly associated with high tumor grade and advanced TNM stage in KIRC, and showed a significant association with an unfavorable prognosis in patients with KIRC." (PMID 37365518, 2023). "This review focuses on KAT8, summarizing its molecular mechanisms in regulating tumor development by catalyzing substrate protein acetylation, which impacts tumor cell proliferation, cell cycle regulation, apoptosis, DNA damage repair, and autophagy." (PMID 40508066, 2025). "Multiple studies have revealed that KAT8 exerts distinct regulatory effects on tumor cell proliferation depending on its expression level (high/low) in tumor tissues." (PMID 40508066, 2025). "By contrast, overexpression of KAT8 dramatically inhibited tumor growth, and the suppressive effect was abolished by MG149 in normal C57BL/6 mouse xenograft model." (PMID 39972392, 2025). "In a high-lactate-induced Colorectal Cancer (CRC) mouse model, KAT8’s tumor-suppressive role was validated, offering new insights into potential therapeutic targets." (PMID 40484921, 2025). "This suggests the heterogeneity of lactylation enzyme KAT8 in different tumour types as well as potential differential gene regulation mechanisms." (PMID 40259204, 2025). "Paradoxically, however, KAT8 is overexpressed in some cancers but underexpressed in others, highlighting its divergent roles in tumor proliferation, apoptosis, and autophagy." (PMID 40508066, 2025). "Further pathway enrichment showed that KAT8 is enriched in tumour‐related pathways such as translation, mitosis and the cell cycle." (PMID 40984037, 2025). "Xenograft study showed that overexpression of KAT8 suppressed tumor growth, whereas silencing of SEPP1 attenuated the tumor suppressive effect of KAT8 in vivo." (PMID 39972392, 2025). "In summary, KAT8 regulates tumor cell proliferation by modulating the cell cycle, tumorigenicity, and related pathways." (PMID 40508066, 2025). "The findings reveal a critical role of the KAT8/YEATS4 axis in both tumor growth and cisplatin sensitivity in BC cells, potentially generating a novel therapeutic strategy for BC patients." (PMID 38526153, 2024). "In contrast, disruption of this connection between IRF1 and KAT8 resulted in decreased cellular PD-L1 levels, decreased tumor mass, and increased numbers of tumor-infiltrating CD8+ T cells." (PMID 38396830, 2024). "KAT8 participates in cell proliferation, tumor invasion, DNA repair, autophagy and transcription regulation." (PMID 36849520, 2023). "The effects of post-translational modification (PTM) of KAT8 on cellular processes and tumor progression have received increasing attention." (PMID 36849520, 2023). "The Codel group demonstrated elevated KAT8 expression across various tumour grades." (PMID 40259204, 2025). "The knockout of KAT8 significantly inhibits tumour cell proliferation." (PMID 40984037, 2025). "This trend aligns with studies that have shown that younger patients often have a higher metabolic turnover in tumour cells, which might lead to increased lactate production and thus higher KAT8 expression." (PMID 40259204, 2025). "To explore the potential impact of lactylation on immune cell activity, we analysed whether KAT8 expression levels correlated with immune cell abundance in the tumour microenvironment (TME) using the TIMER database." (PMID 40259204, 2025).
tumor (continued). "Inhibiting the acetyltransferase activity of KAT8 could suppress the repair of elevated DNA damage in tumor cells, offering a strategy for developing chemotherapeutic agents or adjuvant therapies for radiotherapy/chemotherapy." (PMID 40508066, 2025). "Additionally, KAT8’s role in CRC suppression, the tumor resistance mechanisms associated with NBS1 K388 blockade, and the enhanced tumor-suppressive effects observed with the combination of Sirt2 inhibitors and Elesclomol have also been highlighted." (PMID 40484921, 2025). "KAT8 plays a dual role in the tumor, acting as a suppressor or promoting tumor growth." (PMID 37365518, 2023). "However, the role of KAT8 in tumor progression and how KAT8 regulates the tumor immune microenvironment remain poorly defined." (PMID 36894639, 2023). "KAT8 depletion was shown to promote migration and invasion of tumor cells recently." (PMID 36849520, 2023). "Pharmacological inhibition of CDK1 using RO-3306 suppresses KAT8 phosphorylation and H4K16 acetylation, leading to significant tumor growth inhibition." (PMID 42193906, 2026). "They focused on eEF1A2, a protein that regulates tumor progression via PTM, which led to identifying KAT8 as the “writer” responsible for eEF1A2-Kla." (PMID 40484921, 2025). "KAT8 catalyzed the acetylation of SEPP1 at K247/249 and modulated the activity of CD8+ T cells via LRP8 to promote anti-tumor immunity in PC." (PMID 39972392, 2025). "Conversely, miR-15a and miR-16-1 downregulated KAT8 expression in chronic lymphocytic leukemia cells, decreasing BCL2 levels and, thereby, tumor cell proliferation." (PMID 40508066, 2025). "In rodent models of glioma, KAT8 activity, which mediates H4K16 acetylation, has been related to microglia conversion from an immune tumour counterpart to a tumour-supporting layer." (PMID 39595195, 2024). "In this study, we found that acetylation of YEATS4 by KAT8 promotes YEATS4 protein stabilization, which contributes to DNA repair and BC tumor growth." (PMID 38526153, 2024). "Here, we demonstrate that acetylation of YEATS4 by the histone acetyltransferase KAT8 stabilizes YEATS4 via impairing its binding to E3 ligase HUWE1 and promotes BC tumor growth and that targeting the KAT8/YEATS4 axis suppresses tumor growth and sensitizes BC cells to cisplatin." (PMID 38526153, 2024). "Specifically, in BC cells, KAT8‐mediated YEATS4 acetylation at K64, 65, and 69 promotes YEATS4 stabilization by blocking its HUWE1‐dependent degradation, which in turn contributes to DNA repair and tumor growth and consequently results in DDP resistance." (PMID 38526153, 2024). "In A549 NSCLC cells, KAT8 interacted with and acetylated LSD1, inhibiting LSD1 activity, which increased the methylation of histone H3 at lysine 4 in the promoters of KRT8 and cadherin 1 (CDH1/E-cadherin), upregulating their expression and promoting EMT and tumor invasion." (PMID 40508066, 2025). "The acetylation of FASN by lysine acetyltransferase 8 (KAT8) triggers FASN degradation through the ubiquitin‒proteasome pathway mediated by the E3 ubiquitin ligase TRIM21, leading to a reduction in de novo lipogenesis and tumor cell growth, whereas HDAC3 catalyzes FASN deacetylation." (PMID 39551780, 2024). "Inhibition of KAT8 by MG149 suppresses YEATS4 acetylation, leading to an increase in HUWE1 binding to YEATS4, and therefore facilitating HUWE1‐mediated YEATS4 ubiquitination and proteasomal degradation, which subsequently reduces DNA repair and tumor growth and enhances DDP sensitivity." (PMID 38526153, 2024).
tumor (continued). "Moreover, PINK1 silence downregulates the autophagy receptor p62, inhibiting mitophagy and promoting renal cancer cell proliferation, which suggests that the role of KAT8 in activating the PINK1 signaling pathway could induce cancer cell autophagy and influence tumor cell proliferation." (PMID 40508066, 2025). "KAT8 depletion could not further retard tumor growth in mice treated with anti-PD-1." (PMID 36894639, 2023). "Other HATs such as the human homolog of males absent on the first (hMOF/KAT8) as well as the Steroid Receptor Coactivators-1 and -3 (SRC1/NCOA1 and SRC3/NCOA3) have been shown to play tumor and metastasis suppressor and activator roles, respectively." (PMID 24840099, 2014).
cancer (35 papers, 2013 to 2025). A tumor composed of atypical neoplastic, often pleomorphic cells that invade other tissues. "Dysregulated KAT8 expression or enzymatic activity is implicated in neurological disorders, immune diseases, and cancer." (PMID 40508066, 2025). "Abnormal upregulation or downregulation of KAT8 and its associated H4K16ac have been observed in malignant tumors, suggesting its close association with tumorigenesis and progression." (PMID 40508066, 2025). "Dysregulation of KAT8 is associated with the progression of various cancers." (PMID 39972392, 2025). "Additionally, atypical KAT8 expression and/or function can cause abnormalities in a variety of cell processes including the cell cycle, proliferation, DNA damage repair, early embryonic development, as well as different types of cancers." (PMID 38790268, 2024). "This review summarizes the roles of KAT8 in tumorigenesis and progression and the natural compounds and small-molecule drugs targeting KAT8 for cancer therapy." (PMID 40508066, 2025). "Its role in cancer cell apoptosis depends on its role in cancer progression, as reflected by the KAT8 expression level." (PMID 40508066, 2025). "The lack of specificity of MG149 as a KAT8 inhibitor leaves room for new efficient and potent selective KAT8 inhibitors, such as those described in the recently published study looking for new KAT8 inhibitors for cancer treatment." (PMID 38777823, 2024). "In this study, we aimed to reveal the biological and clinical significance of Kbu modification in cancer and to screen and validate lysine acetyltransferase 8 (KAT8) and histone deacetylase 11 (HDAC11) as writer and eraser of Kbu." (PMID 37460462, 2023). "KAT8 of KANSL2 gene encoding, a member of the KANSL protein family, modulates the NSL complex subunit 2 protein belonging to the KAT8/MOF-NSL complex, and it has been discovered to be associated with cancer and neurodevelopmental disorders." (PMID 35191804, 2022). "First, we analysed the expression of the lactylation enzyme KAT8 at the pan‐cancer level." (PMID 40259204, 2025). "Reduction of the YEATS4 protein upon KAT8 depletion might be a general mechanism as similar effects were observed in various cancer cell lines." (PMID 38526153, 2024). "Previous study also identified KAT8 as a key molecule important for cancer cell survival." (PMID 38246894, 2024). "Indeed, despite being only micromolar KAT8i, 19 and 34 exhibited great selectivity over a panel ofKATs and KDACs, also displaying the capability to target KAT8 andto exert cancer-selective antiproliferative effects in cells." (PMID 37155735, 2023). "Furthermore, examining the impact of KAT8 dysregulation in various disease contexts, such as infectious diseases, autoimmune disorders, and cancer, could uncover potential therapeutic strategies targeting KAT8 for immune modulation." (PMID 38790268, 2024). "Thus,the findings of this study suggest the use of 19 and 34 as chemical tools for better defining the biological rolesand the therapeutic potential of KAT8 and support the idea that KAT8inhibition may have therapeutic value for cancer treatment." (PMID 37155735, 2023). "We recently found that the lysine acetyltransferase (KAT) MYST1/KAT8/MOF dually localizes to the nucleus and mitochondria of human cancer cells." (PMID 37813994, 2023).
cancer (continued). "Moreover, 33 of 43 (76.74%) samples from human multiple organ cancer tissue arrays showed synchronized high or low expression levels of KAT8 and PD-L1 as detected by immunohistochemistry (IHC), indicating that there is a positive correlation between KAT8 and PD-L1 in human cancers." (PMID 36894639, 2023). "As a histone modifier, KAT8 has been shown to physically interact with MLL1 and regulate known cancer drivers ATM and TP5348–51." (PMID 32024818, 2020). "In addition, KAT8 repression induces Caspase 3 cleavage and AR-lacking PC3 cells apoptosis, which indicated that the balance of KAT8 acetylation mediated by KAT8 and SIRT1 is dependent on NF-κB activation and corelated with cancer cell apoptosis." (PMID 40508066, 2025).
infection (4 papers, 2024 to 2026). The state of being infected such as from the introduction of a foreign agent such as serum, vaccine, antigenic substance or organism. "The results showed that down‐regulation of KAT8 expression mediated by EV‐A71 infection caused apoptosis in both U87 and A172 cells." (PMID 40259204, 2025). "Therefore, we examined the apoptosis of two cells after the EV‐A71 infection or infection with KAT8 expression." (PMID 40259204, 2025). "Using this cell line, we knocked down KAT8 expression via lentivirus-mediated shKAT8 infection." (PMID 38961108, 2024). "Studies in mice have demonstrated that kat8 knockdown enhances resistance to infection, suggesting that decreased kat8 expression in yellow drum may similarly boost antiviral defenses during bacterial infection." (PMID 39769404, 2024).
neurodevelopmental disorder (2 papers, 2022 to 2025). A behavioral and cognitive disorder with onset during the developmental period that involves impaired or aberrant development of intellectual, motor, or social functions. "Importantly, KAT8 mutations have recently been linked to a new neurodevelopmental disorder." (PMID 41221126, 2025).
neurodegenerative disease (1 paper, 2024). A disorder of the central nervous system characterized by gradual and progressive loss of neural tissue and neurologic function. "Our findings may open new avenues for the design of novel therapeutic approaches targeting KAT8 for neurodegenerative diseases such as PD, in which defective PINK1-mitophagy plays a central role." (PMID 38777823, 2024).
KAT8 also shares sentences with these, for which no sentence is quoted: non-small cell lung carcinoma (12 papers); renal cell carcinoma (9); kidney cancer (2); malignant melanoma (2); osteosarcoma (2); pancreatic cancer (2); atherosclerosis (1); autism (1); autism spectrum disorder (1); bacterial infection (1); cardiomyopathy (1); cardiovascular diseases (1); dementia (1); Hepatic steatosis (1); Hepatitis (1); infectious disease (1); ischemic stroke (1); kidney tumor (1); Koolen-de Vries syndrome (1); liver cirrhosis (1); liver diseases (1); lymph node metastasis (1); major depressive disorder (1); metabolic disease (1); myeloma (1); neurological disorders (1); nonalcoholic steatohepatitis (1); ovarian tumor (1); Pan (1); pulmonary fibrosis (1).
A further 7 diseases each share a sentence with KAT8 in 1 paper.